PLK1 (polo like kinase 1)
Diseases named in the same sentence as PLK1 in open-access papers (continued):
Sharing a sentence is not in itself a finding about the gene and the disease.
lung carcinoma (continued). "The fact that PLK1 suppresses anti-tumor in LUAD is intriguing given that immunotherapy is one of the major therapeutic approaches for lung cancer." (PMID 38885192, 2024). "Because the overexpression of EGFR is noted in 50% of patients with lung cancer and the inhibition of the mitotic regulator polo-like kinase 1 (PLK1) can enhance radiation sensitivity, EGFR-positive NSCLC cells were targeted by the siPLK1-NP." (PMID 39339205, 2024). "O-GlcNAcylation of G6PD facilitates lung cancer while phosphorylation of G6PD by polo-like kinase 1 (Plk1) affects cell cycle progression and cell proliferation of multiple cancers." (PMID 39337387, 2024). "Larger PLK1‐mutated CRC and lung cancer populations are also required to explore the interaction between PLK1 and KRAS mutations in CRC and compare the molecular features between PLK1‐mutated NSCLC and small cell lung cancer, respectively." (PMID 38887977, 2024). "βIII-tubulin, a constituent of the microtubules essential for cell division, and Polo-Like Kinase 1 (PLK1), a pivotal enzyme in cell cycle regulation and DNA damage response, are overexpressed in lung cancer cells, promoting tumor growth." (PMID 39204314, 2024). "Pkmyt1, Plk1, and Ttk are upregulated in lung cancer and are considered oncogenes due to their function in promoting cell proliferation." (PMID 39273313, 2024). "Another important note is that our investigations have centered on LUAD, and the biological significance of the PLK1-AHR interaction in other lung cancer subtypes remains to be studied." (PMID 37988371, 2023). "This evidence suggests that the CASF-modified liposome/PLK1 gene knockout system can effectively improve the transfection efficiency and enhance the inhibitory ability of lung cancer cells while reducing toxicity to normal lung cells." (PMID 38140096, 2023). "Through transcriptomeanalysis of lung cancer patients, PLK1 was determined as a druggablesynergistic partner to complement HASPIN inhibition." (PMID 37396870, 2023). "Our analysis revealed higher PLK1 expression in lung cancer cell lines (LUAD, LUSC, SCLC) compared to normal lung cells, underscoring PLK1’s role as an oncogene." (PMID 37988371, 2023). "The CASF/Lip/pDNA complex was transfected into lung cancer cells A549 to investigate the transfection efficiency, the PLK1 gene knockout effect and the inhibitory effect on lung cancer cells." (PMID 38140096, 2023). "Considering its importance in lung cancer, novel therapies targeting PLK1 have been developed with observable efficacy in lung cancer cells and animal models." (PMID 37988371, 2023). "The research described here illustrates how superior responses can be achieved for lung cancers by combining PLK1 inhibition with PD-L1 blockade." (PMID 35871223, 2022). "In lung cancer PLK1 expression not only negatively correlated with numerous immune cell lineages, but was also crucial in antigen processing and presentation." (PMID 35719948, 2022). "Here the authors design a nanosystem for the co-delivery of a PLK1 inhibitor and PD-L1 antibody, showing anti-tumor immune responses in preclinical lung cancer models." (PMID 35871223, 2022). "PLK1 expression is dysregulated in several human cancers, including melanoma, breast, colorectal, gastric, and lung cancers." (PMID 36186436, 2022). "We further investigated the PLK1 expression in other cell models, including cisplatin-sensitive and cisplatin-resistant H460 lung cancer cells and A2780 ovarian cancer cells." (PMID 35910374, 2022). "FZD9-/- adenomas had significantly higher expression of polo-like kinase 1 (PLK1) and cyclin D1, which are associated with altered cell cycle control in lung cancer." (PMID 35924166, 2022).
lung carcinoma (continued). "The OS analysis in 1144 lung cancer patients revealed that the expression levels of PLK1 and EGFR mRNA and the OS rates were correlated inversely in human lung cancer (n = 1144, HR = 1.83, log rank P = 6.3 × 10−13)." (PMID 34503223, 2021). "To explore an epigenetic mechanism driving the differential expression of PLKs in lung cancer, we investigated the promoter methylation level of PLK1/2/3/4 in lung adenocarcinoma and lung squamous cell carcinoma." (PMID 34080290, 2021). "Overall, these results in two lung cancer subtypes from TCGA corroborated the findings of PLK1/2/3/4 expression from Oncomine database." (PMID 34080290, 2021). "Next, we aimed to distinguish the differential expression of PLK1/2/3/4 between genders of patients with lung cancer subtypes." (PMID 34080290, 2021). "Higher mRNA expressions of PLK1/4 were significantly related to male patients with either of lung cancer subtype, and higher mRNA expression of PLK3 was apparently associated with female patients with lung adenocarcinoma." (PMID 34080290, 2021). "Further corroborating the antagonistic role of autophagy, the clinically approved autophagy inhibitor chloroquine potently enhances the cytotoxicity of FGFR1/PLK1 inhibitors in KRAS‐mutant lung cancer cells in vitro and in vivo." (PMID 34369083, 2021). "In conclusion, mTORC1/S6K/Akt/PLK1 signaling plays a critical role in maintaining the stability of TCTP protein in lung cancer cells, thereby conferring resistance to DNA-damaging anticancer drugs." (PMID 34675258, 2021). "Our recent studies revealed that paclitaxel-resistant prostate and lung cancer upregulate the level of PLK1 with ABC transporters." (PMID 34503223, 2021). "Global methylation survival analysis showed that prognostic value of PLK1/2/4 methylation remained the same significant trend between two lung cancer subtypes, whereas prognostic value of PLK3 methylation lacked consistency." (PMID 34080290, 2021). "We further focused on the clinical relevance between expression of EGFR/PLK1 and survival rates in lung cancer patients." (PMID 34503223, 2021). "In summary, these immunohistochemistry images basically supported that PLK1/2/3/4 proteins were in accordance with their transcriptional expression in lung cancer." (PMID 34080290, 2021). "Since PLK1/2/3/4 exhibited differential expression in lung cancer subtypes, we carried out to a biological analysis including protein‐protein interaction, GO and KEGG pathway enrichment." (PMID 34080290, 2021). "The clinical relationship between PLK1 or vimentin and cumulative OS in lung cancer was analysed using KM PLOTTER." (PMID 33963314, 2021). "Given that we found the differential expression of PLK1/2/3/4 in lung cancer, further identification of PLK1/2/3/4 expression pleads for an observation of their expression in lung cancer subtypes, including lung adenocarcinoma and lung squamous cell carcinoma." (PMID 34080290, 2021). "Our findings revealed the correlation between mRNA levels of PLKs and DNMTs, providing a new insight into epigenetic regulation of PLK1/2/3/4 expression in lung cancer subtypes." (PMID 34080290, 2021). "After examining the transcriptional expression of PLK1/2/3/4 in lung cancer, we continued to compare the protein expression patterns of PLK1/2/3/4 in both lung adenocarcinoma and lung squamous cell carcinoma." (PMID 34080290, 2021). "We noticed that genetic depletion of FGFR1 increased PLK1 activity and PLK1 reduction upregulated FGFR1 in KRAS‐mutant lung and pancreatic cancer cells, suggesting that FGFR1‐ and PLK1‐mediated pathways reciprocate in KRAS‐mutant lung cancer." (PMID 34369083, 2021). "Then, we sought to determine the correlation between the expression of EGFR and PLK1 and tumorigenesis in lung cancer patients." (PMID 34503223, 2021).
lung carcinoma (continued). "Fourth, we found that combination treatment with inhibitors of USP7 and the mitotic kinase PLK1 shows a strong synergism in taxane-resistant lung cancer through down-regulation of MDR1/ABCB1." (PMID 33207738, 2020). "We found that exogenous RFP-tagged PLK1 proteins were dominantly higher in metastatic lung cancer expressing TD than in lung tissue expressing WT or FA." (PMID 31548612, 2020). "PLK1 inhibition is lethal in K-RAS mutant cells as described in lung cancer, and in OC, synthetic lethality is produced with PLK1 inhibition and paclitaxel in CCNE1 amplified HGSC cells." (PMID 32268485, 2020). "In previous studies, elevated Plk1 expression levels were correlated with invasion in several tumor types, such as colon carcinoma, bladder cancer, thyroid cancer, and lung cancer." (PMID 30859681, 2019). "Another report on human lung cancer indicated that miR-509-3-5p induced G2/M arrest and inhibited the proliferative ability of A549 cells by suppressing PLK1 expression." (PMID 31754397, 2019). "The underlying mechanisms for the induction of apoptotic cell death after Plk1 inhibition were further investigated in cholangiocarcinoma and lung cancer." (PMID 30859681, 2019). "Encouraged by the in vitro activity, we next investigated the in vivo effect of Plk1 and cMet inhibition for the treatment of lung cancer in PDX and cell line xenograft models of NSCLC." (PMID 31040125, 2019). "In human lung cancer A549 cells miR-509-3-5p downregulates PLK1 expression by targeting PLK1 3 ́-UTR and acting as a cancer suppressor." (PMID 29383199, 2017). "Accordingly, it was recently found that TBK1 is activated at mitosis in A549 cells and that loss of TBK1 impaired mitotic phosphorylation of the mitotic Polo-like kinase 1 (Plk1) in TBK1-sensitive lung cancer cells." (PMID 25923723, 2015). "To test this idea, we examined the ability of ligands to sensitize lung cancer cells to different concentrations of PLK1 inhibitor." (PMID 22248814, 2011). "We investigated the effects of PLK-1 siRNA on the liver metastasis of lung cancers using atelocollagen as a DDS." (PMID 21884621, 2011). "Studies on the expression of PLK1 have been performed on carcinomas of lung, head and neck, oesophagus and stomach, skin, breast, brain, endometrium and ovary." (PMID 14970859, 2004). "Additionally, there are studies reported that PLK1 inhibition suppresses Rb phosphorylation in lung cancer." (PMID 40612941, 2025). "Moreover, USP7 appears to play a key role in lung cancers resistant to Paclitaxel through the regulation of two proteins involved in cell mitosis: Serine/threonine-protein kinase or polo-like kinase 1 (PLK1) and BUB3 Mitotic Checkpoint Protein (BUB3)." (PMID 41157055, 2025). "Consistent with our findings in lung cancer TMB, there were no mutations obviously enriched in lung cancers with PLK1 Other mutations, whereas considerable mutated genes were more common in CRCs with PLK1 Other mutations." (PMID 38887977, 2024). "Through the use of mouse models simulating the onset of lung cancer and genetic sequencing analysis, we’ve discovered that high level of PLK1 hinders the immune response, making it challenging for the patient’s immune system to effectively eliminate lung cancer." (PMID 38885192, 2024). "Elevated PLK1 level specifically increases the presence of M2 macrophages, a type of immune cell, which, in turn, prevents the immune system from recognizing and attacking lung cancer cells." (PMID 38885192, 2024). "Our research has pinpointed a vital protein, PLK1, in the development of lung cancer." (PMID 38885192, 2024).
lung carcinoma (continued). "Interestingly, recent studies have validated PLK1 as a potential target to improve the efficacy of immunotherapies in lung cancer, consistent with our findings in pancreatic cancer that targeting PLK1 enhances the effectiveness of immune checkpoint blockade." (PMID 38885192, 2024). "Besides considerable PLK1 missense mutations, various truncating mutations were observed, especially in CRC, in which truncating mutations were more common than in lung cancer (p = 0.02)." (PMID 38887977, 2024). "Therefore, future research needs to dissect the potential molecular functions of PLK1 and AHR in these less explored lung cancer variants." (PMID 37988371, 2023). "Compared with the Lip/pDNA binary complex, the CASF/Lip/pDNA ternary complex-formed CRISPR–Cas9 gene knockout system could more effectively knock out the PLK1 gene and inhibit the proliferation of lung cancer cells." (PMID 38140096, 2023). "The fibroin-modified liposome/PLK1 gene knockout system not only effectively inhibited the growth of lung cancer cells but also showed no obvious toxicity to normal cells, showing potential for clinical application in lung cancer therapy." (PMID 38140096, 2023). "Polo-like protein kinase 1 (PLK1) plays a key role in lung cancer cell mitosis." (PMID 38140096, 2023). "Because PLK1 was often upregulated in lung cancer and promoted tumor growth, suppression of PLK1 could reduce cancer growth." (PMID 37033636, 2023). "These preclinical findings are exceptionally promising, and further studies of PLK1 could significantly fortify the groundwork for advancing PLK1-based therapies in lung cancer patients’ treatment." (PMID 37988371, 2023). "Furthermore, GW843682x, a polo-like kinase 1 inhibitor, has been found to disrupt spindle formation and induce abnormal mitotic processes in lung cancer cells." (PMID 37633093, 2023). "Recently, several studies report that PAIP1 could regulated expression of AKT/GSK-3 β signaling pathway genes in lung cancer, Ki67, Pcna, Bax/Bcl2 and caspase-3 in tongue squamous cell carcinoma, and PLK1 in gallbladder cancer, respectively." (PMID 37101794, 2023). "Therefore, LJ4827 is a novel anticancer therapeuticfor selectively impeding cancer mitosis through potent HASPIN inhibition,and simultaneous HASPIN and PLK1 interference is a promising therapeuticstrategy for lung cancer." (PMID 37396870, 2023). "In addition, studies have shown that inhibition of PLK1 promotes tumor cell apoptosis in lung cancer." (PMID 35840978, 2022). "This study reports a synergistic drug combination by targeting FGFR1 and PLK1 and identifies autophagy as a protective mechanism that limits the efficacy of FGFR1/PLK1 inhibitor therapy in KRAS‐mutant lung cancer, suggesting a novel strategy to treat the daunting disease." (PMID 34369083, 2021). "In addition, global methylation survival analysis showed that prognostic value of PLK1/2/4 methylation kept a similar trend between two lung cancer subtypes, whereas prognostic value of PLK3 methylation showed different between subtypes." (PMID 34080290, 2021). "Because of oocyte meiosis pathway mediated by PLK1, we found that transcriptional expression of PLK1 decreased in female patients with either of lung cancer subtypes, which indicated that PLK1‐mediated pathway preferred to facilitate a development of lung cancer in male patients." (PMID 34080290, 2021). "The PLK1 was significantly overexpressed in patients with lung cancer in six data sets." (PMID 34080290, 2021). "An understanding of how PLK1/4 contributes to tumorigenicity of lung cancer in male patients may enable their use as a therapeutic target for distinct gender patients." (PMID 34080290, 2021). "The CDK7 and PLK1 inhibitors played a critical role in immunotherapies for lung cancer." (PMID 34721732, 2021). "Previously, we found that PLK1 is highly expressed in taxane-resistant prostate and lung cancer." (PMID 33207738, 2020).
lung carcinoma (continued). "We performed immunoblot analyses of lung tissue or metastatic lung cancer tissue from each mouse to evaluate whether cells expressing PLK1 had metastasized to the lung and if so, which factors were expressed in the metastatic cancer." (PMID 31548612, 2020). "Additionally, PLK1 expression is much higher in tumor tissues than in adjacent normal tissues in certain types of cancer, such as lung cancer (20.8-fold), cholangiocarcinoma (24.3-fold), and uterine corpus endometrial carcinoma (21.3-fold)." (PMID 31387297, 2019). "PLK1 was one of the most extensively studied genes in cell cycle regulation, and it was highly expressed in various cancers, especially in gastric cancer, lung cancer, and pancreatic carcinoma." (PMID 31139019, 2019). "The interacting genes’ expression in the PLK1-MCM complex-SKP2 subnet of NSCLC patient datasets is weakly positively correlated or negatively correlated in normal samples but positively correlated in lung cancer samples." (PMID 22838965, 2012). "In this review, we discuss possible RNAi strategies against PLK-1 in advanced lung cancers." (PMID 21884621, 2011). "Here we introduce an application of PLK-1 siRNA against an advanced lung cancer." (PMID 21884621, 2011). "This hypothesis matches well with observations that PLK1 expression is a survival parameter in oesophageal carcinoma, lung carcinoma and squamous cell carcinoma of head and neck, and serves as a marker for metastatic disease in malignant melanoma." (PMID 14970859, 2004). "Thus, dual-target PLK1/NRP1 inhibitor (PLN-5) may represent a potential therapeutic strategy in lung cancer." (PMID 40820676, 2025). "Moreover, PLK1 is highly expressed in paclitaxel-resistant prostate and lung cancer." (PMID 33207738, 2020). "Similarly, our study also showed that PLK1 expression was increased in lung cancer tissues." (PMID 28724602, 2017). "Considering that PLK1 and NRP1 are essential for lung cancer development, targeting PLK1 and NRP1 simultaneously represents a potential therapeutic approach for lung cancer." (PMID 40820676, 2025). "In conclusion, PLN-5 is a potent dual-target inhibitor of PLK1 and NRP1 and is expected to be further developed for the treatment of lung cancer." (PMID 40820676, 2025). "To summarize, based on the genomic landscape under natural selection within lung cancer and CRC tumours, the clinical application of PLK1 inhibitors still needs to be approached with caution given potent tumour‐suppressor features of PLK1." (PMID 38887977, 2024). "Using previously published microarray data of lung cancer (GSE 114761), FoxM1 and PLK1 were upregulated in TGF-β-induced EMT in A549, NCI-H522, NCI-H1944, and NCI-H2122 cells." (PMID 37968723, 2023). "The results showed PLK1, LDHA, FURIN, FSCN1, and RAB27B were up-regulated in lung cancer tissues, and MS4A1 was down-regulated in lung cancer tissues." (PMID 37604869, 2023). "Better inhibition of EGFR-mutant lung cancer cells was observed with the combination of EGFR and PLK1 inhibitors compared to EGFR inhibition alone." (PMID 37174055, 2023). "We studied two important proteins in lung cancer: aryl hydrocarbon receptor (AHR) and Polo-like kinase 1 (PLK1), which are known to worsen many types of cancer." (PMID 37988371, 2023). "The less abundant expression of AHR and lack of survival evidence in SCLC patients led to our less focus on this lung cancer subtype, and we then investigated the significance of AHR and PLK1 in other two lung cancer subtypes." (PMID 37988371, 2023). "Our research demonstrated that the interaction between AHR and PLK1, the role of DIO2, and thyroid hormones were significant factors in lung cancer cells spread." (PMID 37988371, 2023). "Elevated PLK1 expression was negatively correlated with overall survival (OS) of PAAD and lung cancer patients analyzed from TCGA database." (PMID 38104151, 2023).